RN7SL214P (RNA, 7SL, cytoplasmic 214, pseudogene)
Gene: Miscellaneous RNA gene on chromosome 15 (77,916,718 to 77,916,982, reverse strand). Ensembl gene ENSG00000242066.
Homologues: Orthologues: chimpanzee Metazoa_SRP (89% identical), chimpanzee Metazoa_SRP (88% identical), chimpanzee Metazoa_SRP (81% identical), macaque Metazoa_SRP (62% identical), pig Metazoa_SRP (56% identical). Paralogues in human: RN7SL536P (87% identical), RN7SL736P (87% identical), Metazoa_SRP (87% identical), RN7SL106P (87% identical), RN7SL238P (87% identical), RN7SL545P (87% identical), RN7SL759P (87% identical), RN7SL417P (86% identical), RN7SL196P (83% identical), RN7SL286P (83% identical), RN7SL539P (83% identical), RN7SL796P (83% identical), and 705 more.